CD4 (CD4 molecule)
Diseases named in the same sentence as CD4 in open-access papers (continued):
Sharing a sentence is not in itself a finding about the gene and the disease.
pulmonary TB (continued). "In this prospective cohort study of persons with HIV (CD4 counts>350 cells/mm3) and pulmonary TB we measured a significant decline in CD8 T cell immune activation that persisted for at least 6 months after completion of TB therapy." (PMID 20179751, 2010). "In the lowest CD4 count range (<100/mm3), PcP was common, although the incidence was low compared with that of bacterial pneumonia and pulmonary tuberculosis." (PMID 17479904, 2007). "Our results have demonstrated that CD27-expression on ex-vivo short term stimulated tuberculin specific CD4 T-cells is a highly discriminating biomarker for active pulmonary TB." (PMID 17710135, 2007). "This work was done on blood cells rather than pulmonary lymphocytes; however, we discovered that the measurement of CD27 expression on tuberculin-reactive human CD4 T-cells is a useful and rapid tool for the diagnosis of active pulmonary tuberculosis." (PMID 17710135, 2007). "PcP incidence was highest in patients with the lowest CD4 counts but uncommon compared with incidences of pulmonary tuberculosis and bacterial pneumonia." (PMID 17479904, 2007). "With a significant percentage of extra pulmonary and sputum-negative cases linked to CD4 counts < 200 cells/μL, pulmonary TB wasshown to be the most prevalent type among HIV-infected individuals in this investigation." (PMID 40978657, 2025). "In addition, an elevated proportion of CD4+CD25+CD127low Tregs indicates an increase in immunosuppressive effects among patients with active pulmonary TB, leading to imbalanced immune responses and immune tolerance." (PMID 36035072, 2022). "Overall, these results suggest that assessing the activation profile of Mtb-specific CD4 T cells could aid monitoring of treatment response in extra-pulmonary TB." (PMID 36439130, 2022). "Our data indicate that the downregulation of PD-1/PD-L1 expression may promote the proliferation of peripheral blood CD4+CD25+CD127low Tregs among patients with active pulmonary TB." (PMID 36035072, 2022). "Finally, the association of PD-1 and PD-L1 expression with proportions of peripheral blood CD4+CD25+CD127low Tregs was examined among active pulmonary TB patients using Pearson correlation analysis." (PMID 36035072, 2022). "However, this patient lost immune control and CD4+ T cell counts dropped when she was diagnosed with extrapulmonary/disseminated TB along with a pulmonary TB (green arrow)." (PMID 33489013, 2021). "For example, in one study the percentage of CD4+CD25hi cells expressing FoxP3 was the same in both study groups, but the percentage of CD4+CD25hiFoxP3+ relative to total CD4+ cells was significantly different between healthy donors and patients with pulmonary TB (PTB)." (PMID 31572365, 2019). "We have previously shown that persons with previous extrapulmonary TB appeared to have a subtle immune defect with decreased cytokine production and lower CD4 lymphocyte counts compared to persons with previous pulmonary TB, persons with LTBI and uninfected contacts." (PMID 31039752, 2019). "Similarly, the increased expression of IL-19 and IL-24 in active pulmonary tuberculosis patients also mediated decreased expression of Th1/Tc1 and Th17/Tc17 cytokine in CD4+ and CD8+ T cells." (PMID 31921658, 2019). "Taken together, these data provide further evidence that high bacterial loads in patients with smear+ TB disease drive increased expression of PD-1 on Mtb-specific CD4 T cells, and that PD-1 expression decreases on Mtb-specific CD4 T cells following successful treatment of pulmonary TB." (PMID 30233588, 2018). "CD4+ T cells play a dominant role in host defense during active pulmonary TB." (PMID 29176787, 2017). "Low CD4 T-cell counts, high HIV RNA levels and/or the presence of pulmonary tuberculosis at V0 associated with low BMI, smaller diameter of the carotid artery and/or higher systolic blood pressure, but not consistently with markers of cardiovascular health assessed at any time." (PMID 28859681, 2017).
pulmonary TB (continued). "Overall, the observational evidence suggest HIV-infected individuals with low levels of vitamin D may be at increased risk of mortality, pulmonary TB, HIV disease progression, have poorer CD4 T cell reconstitution when on ART." (PMID 28183335, 2017). "A change in the ART eligibility criteria for adults from a CD4+ T-lymphocyte count of 200 cells/μl to 350 cells/μl could have contributed to a decrease in extra-pulmonary tuberculosis, as the latter usually occurs in severely immunocompromised persons." (PMID 27669564, 2016). "Significantly higher levels of circulating soluble CD14 (sCD14), a non-specific marker of macrophage activation, were found in HIV/TB co-infected patients with pulmonary TB as compared to CD4-matched HIV-1 infected healthy subjects, that was irrespective of their CD4 T cell count." (PMID 27870882, 2016). "However, an increase in the in vitro percentage of CD4+CD25HighFoxP3 cells was observed in active pulmonary tuberculosis patients in stimulated cultures (P = 0.029 resp., Kruskal-Wallis test followed by Dunn's post hoc test)." (PMID 26000298, 2015). "Thus, active pulmonary TB appears to be characterized by an antigen-responsive expansion of IL-10+ CD4+ T cells that also are producing more IL-10 per cell." (PMID 26417443, 2015). "Furthermore, study participants with baseline CD4+ of 351-500cells/ul were about two times more likely to have symptomatic stage 3 disease such as recurrent diarrhoea and pulmonary tuberculosis than those with baseline CD4+ >500cells/ul." (PMID 25933356, 2015). "Thus, co-existent helminth infection is associated with an IL-10 mediated (for filarial infection) profound inhibition of antigen-specific CD4+ T cell responses as well as protective systemic cytokine responses in active pulmonary TB." (PMID 25211342, 2014). "Since CD4+ alveolar lymphocytosis in the healthy zone of patients with localized pulmonary tuberculosis was reported previously, an increased CD4+/CD8+ ratio in BAL may imply intense immunosensitivity toward BCG antigens." (PMID 24593234, 2014). "In this study, BCG-vaccinated controls had significantly fewer CD27‒CD4+ T-cells than patients with smear and/or culture positive pulmonary tuberculosis allowing for discrimination between these groups with high sensitivity and specificity whereas individuals with LTBI exhibited levels in-between." (PMID 24376464, 2013). "This could be due to the overall shorter interval between starting ATT to ART initiation, the lower median CD4+ T-cell count and the fact that all patients had confirmed (culture-positive) pulmonary TB cases." (PMID 23691062, 2013). "On the other hand, some studies indicate that CD3+ and CD4+ cell counts may be higher in drug-sensitive pulmonary TB cases." (PMID 23626814, 2013). "Our univariate analysis found that AFB smear-negative pulmonary TB was significantly associated with fever, chills, CD4+ cell level < 200/mm3, and TB-CXR." (PMID 23227329, 2012). "An independent-samples t-test showed an increased frequency of CD4+ T cells expressing IFN-γ (p = 0.034) and a significantly decreased frequency of CD4+ T cells expressing IL-2 (p = 0.037) - both ESAT-6 specific - in patients with pulmonary TB when compared to diseases other then TB." (PMID 22523581, 2012). "In conclusion, this study documents that there is no deficiency in the differentiation of effector CD4 T cells during severe pulmonary TB." (PMID 22937086, 2012). "To test this hypothesis, in the present study we evaluated the degree of CD27hi→CD27low differentiation of CD4 T cells in patients with pulmonary TB." (PMID 22937086, 2012). "Other studies in HIV negative individuals with lung TB underline the potential role of Treg since increased frequencies of both total CD4+CD25+ T cells and CD4+ CD25high cells were shown during active disease, preferably in the involved lung." (PMID 22431997, 2012).
pulmonary TB (continued). "Here we addressed our hypothesis by evaluating CD27lowMtb-specific CD4 T cells in patients with pulmonary TB." (PMID 22937086, 2012). "The second patient had a CD4 count of 575 cells/μL and was diagnosed with pulmonary TB." (PMID 21528786, 2011). "To test this hypothesis we prospectively followed a cohort of 38 HIV positive persons with baseline CD4 counts >350 cells/mm3 in Uganda who had smear and culture confirmed pulmonary TB and was placed on standard anti-TB therapy." (PMID 20179751, 2010). "Furthermore, apoptosis of Mycobacterium tuberculosis-reactive CD4+ and non-CD4+ T cells seems to be increased in pulmonary TB patients." (PMID 20479873, 2010). "Compartmentalization of the CD4(+) T lymphocytes in the infected lungs with a reciprocal decrease in peripheral blood counts of the same lymphocyte subset has been demonstrated in patients with higher grades of pulmonary TB." (PMID 20113509, 2010). "Furthermore a ratio of combined ESAT-6 and CFP-10 peptide ELISPOT count divided by the CD4+ T-cell count greater than 0.21 had 100% sensitivity and 80% specificity for active pulmonary TB." (PMID 18226199, 2008). "Peripheral blood CD8+ percentage and NKT cells may be indicators for the clinical auxiliary diagnosis of active pulmonary TB, whereas CD4+ percentage decreases with the aggravation of the disease, which can be used as an indicator to judge the severity of pulmonary TB." (PMID 38650928, 2024). "Interestingly, according to our results, the persistence of low post-treatment CD4+ levels in active pulmonary TB groups (only TB, TB-DM) was significantly lower than only the DM group and healthy subjects, indicating an absence of cellular immunity recovery after 2 months of treatment." (PMID 37764989, 2023). "Concomitantly with the increase in BAL lymphocytes, blood CD4+ cells doubled in their proliferative capacity to PPD or Mtb culture filtrate protein stimulation (data not shown) at the 4 week time point in both immunoadjunctive rIFN-γ1b groups of drug-sensitive pulmonary tuberculosis." (PMID 19753300, 2009). "Median CD4+ cell counts were lower in extrapulmonary tuberculosis patients (126.5 cells/μL, IQR: 44.25–225.75) compared to pulmonary tuberculosis patients (264.0 cells/μL, IQR: 84.75–442.0), though this difference was not statistically significant (p = 0.21)." (PMID 40407641, 2025). "Using IPDA, we documented significantly higher levels of intact, fragment, and total HIV proviruses in circulating CD4+ T cells of people living with HIV and a history of bacteriologically confirmed pulmonary TB." (PMID 39345793, 2024). "Of the 200 participants, 120 (60%) were male, 73 (37%) were HIV positive (median CD4 120 cells/uL (IQR 43–297)) and 128 (64%) had confirmed pulmonary TB by sputum MGIT culture." (PMID 37083706, 2023). "The increased expression of PD-1 on CD4+ T cells and PD-L1 on CD14+ monocytes was evident in pulmonary TB patients, and the increased expression of PD-L1 on CD14+ monocytes was associated with higher bacterial burden and delayed smear/culture conversion." (PMID 35163542, 2022). "The proportions of peripheral blood CD4+CD25+CD127low Tregs and the expression of PD-1 and PD-L1 on CD4+CD25+CD127low Tregs were detected among active pulmonary TB patients using flow cytometry." (PMID 36035072, 2022). "BALF from pulmonary TB patients shows an increase in M. tuberculosis-specific T lymphocytes that have a memory phenotype (C8+CD45RO+/CD4+CD45RO+), but CD4+CD45RO+ constitutes the main source of IFN-γ in supernatants." (PMID 36009042, 2022). "Among the participants who were confirmed positive for pulmonary tuberculosis, 20 (33%) were living with HIV infection, with a median CD4 cell count of 70.5 cells/μL, including 5 (8%) who were on HIV treatment." (PMID 35019686, 2022).
pulmonary TB (continued). "Participants in study 1 included 60 with pulmonary TB and HIV coinfection, 40 with CD4 counts of >200 cells/mm3, and 20 with CD4 counts of <200 cells/mm3, as well as 20 participants living with HIV and without TB (who contributed only genotype data)." (PMID 31964788, 2020). "Earlier studies have shown that HIV co-infected pulmonary TB patients with lower CD4+ T-cell count have detectable LAM in the urine, indicating higher burden of LAM with CD4 + T-cell depletion." (PMID 32611401, 2020). "Using high‐throughput NGS, we sequenced repertoires CD4+ cells, CD8+ cells and tissue samples of nine pulmonary tuberculosis patients and nine normal controls." (PMID 31173489, 2019). "Recently, many studies have also shown an increase in CD4+CD25+FOXP3+ T lymphocytes in the blood and at the site of active infection in pulmonary tuberculosis patients." (PMID 29489879, 2018). "Most of extra-pulmonary TB whether it is abdominal (83.4%), pleural (70%), lymphadenopathy (61.1%), CNS or disseminated TB had CD4 counts below 200, in consonance with the previous studies which show that atypical presentation of TB increase with reduction in CD4 counts." (PMID 30915136, 2018). "Compared to healthy people, CD4+ T cells producing IL-22 and IL-17A have been reported to be upregulated in BAL fluids of pulmonary TB patients, indicating their probable contribution to anti-mycobacterial responses." (PMID 30386336, 2018). "70% of our cohort was HIV infected, with advanced immunosuppression – clinically stage 4 HIV with extra-pulmonary TB (suspected or confirmed TBP), and a median CD4+ T cell count of less than 150 cells/cm3." (PMID 27633798, 2016). "Comparing and analysing these results in the study showed that levels of CD4+CD25+/CD4+,CD4+CD25+Foxp3+/CD4+ and TGF-β1 in pulmonary TB were higher than those in recovered TB patients and healthy controls while IFN-γ were lower." (PMID 23755239, 2013). "Results from the study showed a significant relationship between the CD4 lymphocyte cell count and the radiographic features of HIV positive patients with pulmonary tuberculosis." (PMID 23431432, 2013). "The CD4 T cells were significantly lower in the blood, but CD8 T cells were normal in patients with pulmonary TB when compared with values obtained in normal blood donors." (PMID 23308269, 2013). "PBMCs from patients with pulmonary TB and healthy controls were stained with fluorescence-labeled CD3, CD4 and CD244/2B4 antibodies and analyzed by flow cytometry." (PMID 23638187, 2013). "All clinical parameters (pulmonary tuberculosis, wasting and diarrhea in past 6 months) were significantly elevated in HIV positive women particularly those in lower CD4 strata (p<0.001 for all)." (PMID 22532840, 2012). "Differences between pulmonary TB and other diseases were restricted to increased frequencies of CD4+IFN-γ+ T cells and decreased frequencies of CD4+IL-2+ T cells, contributing independently to the logistic regression model." (PMID 22523581, 2012). "Although pediatric patients presented with similar frequencies of pulmonary TB, far fewer were smear positive (8.7%) but their HIV disease was advanced (CD4+ T-cell count <50 cells/mm3 = 16.2%)." (PMID 22400104, 2012). "Most adults (84.8%) presented with pulmonary TB (34.9% smear positive) and advanced HIV disease (mean CD4+ T-cell count = 216.4 ± 206.8 cells/mm3, CD4+ T-cell count <50 cells/mm3 = 18.4%)." (PMID 22400104, 2012). "In this prospective cohort of newly diagnosed pulmonary TB patients from an HIV endemic, sub-Saharan setting we report a large dataset studying the CD4 lymphocyte dynamics during TB treatment; both in HIV uninfected and HIV infected TB patients." (PMID 22436147, 2012). "In patients with relatively intact immune function (CD4+ lymphocyte count >200/mm3), pulmonary tuberculosis (PTB) is more frequently seen than extra pulmonary TB." (PMID 22738361, 2012).
pulmonary TB (continued). "A previous study of adult pulmonary TB patients showed a significantly lower percentage of CD3+ and CD4+ cells, and a significantly lower ratio of CD4+ and CD8+ cells compared with healthy controls." (PMID 22111973, 2011). "Contributing factors in these studies include low CD4 levels, co-administration of ART, extra-pulmonary TB and treatment for co-morbidities." (PMID 21085569, 2010). "This study investigates factors associated with mortality including patients' HIV sero-status, CD4 cell count, laboratory, nutritional and demographic characteristics in AFB smear positive pulmonary TB patients." (PMID 19909501, 2009). "Furthermore, severe immunosuppression (low CD4 T-lymphocyte counts), a characteristic of advanced HIV infection, increases the odds of having extrapulmonary TB versus pulmonary TB alone." (PMID 38392836, 2024). "At the immune cell level, TB-COPD patients showed a notable decrease in lymphocytes and CD4+ T lymphocytes, implying that COPD combined with pulmonary TB may significantly affect the immune system, leading to a reduction in the counts of key immune cells." (PMID 39432654, 2024). "The apoptosis rate of CD4+ T cells in peripheral blood from patients with sputum-positive pulmonary TB is significantly higher than that of patients with sputum-negative pulmonary TB and healthy controls." (PMID 38004652, 2023). "Conversely, height, current CD4 count, and pulmonary tuberculosis were not significant predictors of FEV1s (l) (p > 0.05)." (PMID 37901155, 2023). "The present study aims to further the understanding of the immune status of patients with TB by using flow cytometry to determine the absolute counts of T lymphocytes, CD4+ and CD8+T lymphocytes, NK lymphocytes, NKT lymphocytes, and B lymphocytes in 217 cases of pulmonary TB (PTB)." (PMID 35522050, 2022). "Additionally, lymphocyte populations present in the lung of pulmonary TB patients are Th1 (CD4+IFN-γ+CXCR3−), Th17 (CD4+IL-17A+CXCR3−), and Th1/Th17 (CD4+IFN-γ+IL-17A+CXCR3−)." (PMID 36009042, 2022). "The proportion of CD4+CD25+CD127low Tregs is higher in patients with active pulmonary TB than in healthy controls, and the negative costimulatory signal PD-1/PD-L1 expression is downregulated among active pulmonary TB patients." (PMID 36035072, 2022). "PD-1 expression was significantly higher on CD4+ T cells in pulmonary TB patients, compared with LTBI cases (p = 0.011) and non-TB, non-LTBI individuals (p = 0.003)." (PMID 35163542, 2022). "In contrast to the up-regulation of BTLA expression in circulating CD4+ and CD8+ T cells, APCs, and DCs, the expression of BTLA was decreased in αβ T cells of active pulmonary tuberculosis patients and anti-tuberculosis drugs induced BTLA expression along with bacterial clearance." (PMID 34163466, 2021). "The diagnosis of HIV-associated TB is especially challenging since HIV co-infected patients form less organized granuloma and have a higher proportion of sputum smear-negative pulmonary TB as well as extra-pulmonary TB, especially at low CD4 counts." (PMID 29495442, 2018). "The presence of CMV DNA did not associate with HIV RNA levels (Mann–Whitney, p = 0.53), CD4 T-cell counts (p = 0.31) or CRP levels (p = 0.81), but was more common in patients with pulmonary tuberculosis (χ2, p = 0.04)." (PMID 28859681, 2017). "In HIV positive patients CD4 level was not taken into consideration and it is well known that pattern of chest X-ray in pulmonary tuberculosis patients is different in high and low level of CD4 level." (PMID 26379713, 2015). "The mean CD4 count in individuals with active pulmonary tuberculosis only (HIV-1/2 negative) was significantly lower than healthy controls [CD4 count (mean±SEM cells/μl): 577±102 vs 817±66, p = 0.0064], though well within the normal range." (PMID 25198707, 2014). "The mean CD4/CD8 ratio was significantly higher in positive smear pulmonary tuberculosis than negative smear (0.59 versus 0.25, P < 0.003)." (PMID 25164493, 2014).